SETD3 (SET domain containing 3, actin N3(tau)-histidine methyltransferase)
Diseases named in the same sentence as SETD3 in open-access papers (continued):
Sharing a sentence is not in itself a finding about the gene and the disease.
adenoma (1 paper, 2013). A neoplasm arising from the epithelium. "Quantitative analysis of microarray data confirmed that these methyltransferases, which included Setd3, Setd5, Suv39h2, Smyd3, Prmt3, Prmt6, Nsd1, and Nsd2 were up-regulated in metastases compared to adenomas, carcinomas, or disseminated cells." (PMID 23520493, 2013).
B-cell lymphomas (1 paper, 2021). "It was previously shown that an SET-domain-lacking fragment of the SETD3 gene translocated to the immunoglobulin lambda light chain locus in B-cell lymphomas, which resulted in the disruption of the SETD3 gene and appearance of a shorter form of the SETD3 protein lacking the SET domain." (PMID 34685411, 2021).
dystocia (1 paper, 2023). Slow or difficult obstetric labor or childbirth. "Recently, mammalian SETD3 was identified to be responsible for the Nτ-methylation of actin at His-73 and SETD3-deficient female mice were found to develop primary maternal dystocia." (PMID 37543365, 2023).
muscular disease (1 paper, 2019). Myopathy is a peripheral nervous system disease consisting of any abnormal condition or disease of the muscular tissues; commonly designates a disorder involving skeletal muscle. "It will also be interesting to determine if miR-15b/miR-322 and SETD3 participate in skeletal muscle degeneration/regeneration process as well as human muscular diseases, such as rhabdomyosarcoma." (PMID 30796205, 2019).
stomach adenocarcinoma (1 paper, 2021). "Among the main TFs-HRi identified, we highlight four TFs (SETD3, HOX3B, FOXA1, and SOX4) for being widely reported in association with stomach adenocarcinoma." (PMID 34416858, 2021).
systemic lupus erythematosus (1 paper, 2021). An autoimmune multi-organ disease typically associated with vasculopathy and autoantibody production. "It was recently shown that the SETD3 protein might be involved in the progression of autoimmune diseases, including systemic lupus erythematosus (SLE)." (PMID 34685411, 2021).
thyroid cancer (1 paper, 2020). "To have an overview of SETD3 expression in different solid tumors, we analyzed its expression in samples from the TCGA, which demonstrated that SETD3 is mainly expressed in renal and thyroid cancer." (PMID 32042016, 2020).
cancer (20 papers, 2013 to 2024). A tumor composed of atypical neoplastic, often pleomorphic cells that invade other tissues. "Consistent with this, Setd3 is implicated in cancer progression and cell cycle control, as well as cytoskeletal integrity." (PMID 35762573, 2022). "Of note, a line of evidence indicates that SETD3 is closely associated with many diseases, including cancers." (PMID 35912180, 2022). "The histone methyltransferase SETD3 plays critical roles in various biological events, and its dysregulation is often associated with human diseases including cancer." (PMID 35018513, 2022). "SETD3 plays an important role in cancer development and is associated with several kinds of cancers." (PMID 35018513, 2022). "The SETD3 protein has been shown to regulate the expression of various genes associated with cancer progression, including FOXM1, ACTB, ASMA, ACTG, FSCN, and FBXW7." (PMID 34685411, 2021). "It seems that SETD3 has different roles in cancer depending on other mutations and the stage of tumor progression." (PMID 32042016, 2020). "We also describe an example of a highly pathogenic somatic duplication that directly overlapped with the SETD3 gene, a histone methyltransferase that is implicated in many diseases, including cancers." (PMID 33168059, 2020). "In addition, other studies also implied that SETD3 is associated with DNA replication or DNA repair, cancer proliferation and metastasis." (PMID 35018513, 2022). "Interestingly, SETD3 regulates the expression of other genes associated with cancer such as β-actin, FOXM1, FBXW7, Fascin, eNOS, and MMP-2." (PMID 32042016, 2020). "Recent papers have also linked the expression of SETD3 to cancer progression." (PMID 27845446, 2016). "Interestingly, SETD3 has been linked to cancer in various ways." (PMID 30067821, 2018). "Cancer type-dependent histone lysine modifiers, like SET-8 and SETD3, carry out the complex functions of HMTs and HDMs, warranting research into their roles in the diagnosis of multiple cancers and their subtypes." (PMID 39765675, 2024). "Some histone lysine modifiers like SET-8 and SETD3 have been shown to have cancer type-dependent effects." (PMID 39765675, 2024). "Several studies published so far have focused on the role of the SETD3 protein in cancer, while only a few have addressed the potential involvement of this protein in other pathologies." (PMID 34685411, 2021). "The available information collectively suggests the importance of SETD3 in the development and progression of cancer, as discussed in the next section." (PMID 34685411, 2021). "Other SETD-domain protein methyltransferases, such as SETD3, have also been considered as therapeutic targets for cancer." (PMID 33339442, 2020). "In several carcinomas, the SET Domain Containing 3, Actin Histidine Methyltransferase (SETD3) is associated with oncogenesis." (PMID 32042016, 2020). "Modulation of SETD3 activity in human cells facilitates cancer-like changes to the cell phenotype." (PMID 39488591, 2024). "Moreover, ectopic expression of NUDT16 greatly enhanced the resistance of cancer cells to IR treatment; however, depletion of SETD3 in these cells overexpressing NUDT16 largely reversed cell sensitivity towards IR exposure." (PMID 38272222, 2024). "Even among different cancer subtypes, the role of SETD3 differs." (PMID 39765675, 2024). "Although the precise role of SETD3 in carcinogenesis is still unclear, available data confirm that the protein might act either as a cancer suppressor or as an oncogenesis-promoting factor." (PMID 34685411, 2021).
cancer (continued). "A further indication that SETD3 might play a role in cancer is the finding that SETD3 is overexpressed at the mRNA and protein level in Renal cell tumors (RCTs)." (PMID 30067821, 2018). "Importantly, depletion of endogenous SETD3 in NUDT16-deficient cells did not further exacerbate DNA breaks or enhance the sensitivity of cancer cells to IR treatment." (PMID 38272222, 2024). "In this study, we revealed that SETD3 regulates cell cycle progression and cell proliferation by decreasing R-loop-induced replication stress and enhances HR repair in response to DNA double-strand breaks, resulting in a substantial increase in the resistance of cancer cells to IR exposure." (PMID 38272222, 2024). "Importantly, depletion of endogenous SETD3 in NUDT16-deficient cells does not further exacerbate DNA breaks or enhance the sensitivity of cancer cells to IR treatment." (PMID 38272222, 2024). "The SETD3 protein may act as a prognostic biomarker in cancer." (PMID 34685411, 2021). "It seems therefore, that SETD3’s roles and involvement in cancer may vary depending on its type." (PMID 30683849, 2019). "Since upregulation of SETD3 can promote liver tumorigenesis and cancer progression, it is possible that USP27 can also enhance metastatic phenotype by stabilizing SETD3." (PMID 35018513, 2022). "Based on host genome integration frequencies, we found previously reported integration sites in cancer for genes like FHIT, CSMD1, and LRP1B and putatively many new ones such as those exemplified in CSMD3, ROBO2, and SETD3." (PMID 33810183, 2021). "SETD3 is responsible for the methylation of H73 in human and Drosophila actin, and a loss of SETD3 activity in human HAP1 cells induces phenotypic changes resembling those present in cancer cells, suggesting that the hypomethylation of actin might be involved in tumorigenesis." (PMID 30526847, 2018). "In this work, we uncover that SETD3 likely regulates PLK1 levels directly, which might provide a combinational way through simultaneous inhibition of PLK1 activity and reduction of PLK1 transcriptional levels to deal with drug resistance of cancer cells." (PMID 35912180, 2022). "Importantly, depletion of SETD3 in NUDT16-deficient cells did not further exacerbate DNA breaks or enhance the sensitivity of cancer cells to IR exposure, suggesting that the NUDT16-SETD3 pathway may play critical roles in the induction of tolerance to radiotherapy." (PMID 38272222, 2024). "Similarly, even though SETD3 is involved in the response to hypoxia in various cancer cell lines, it is not known whether SETD3 is required for an appropriate hypoxia response in normal cells or the whole organism." (PMID 30067821, 2018). "Thus, it seems that the specific role of SETD3 in cancer is still not clear." (PMID 27845446, 2016).
tumor (14 papers, 2013 to 2024). "After the initial characterisation of our experimental system, we aimed to uncover the possible participation of SETD3 in processes associated with tumor progression such as proliferation and invasion." (PMID 32042016, 2020). "The phenotype of Setd3-deficient cells is therefore somewhat similar to that of malignant cells, suggesting that SETD3 activity may play a role in suppressing tumor development." (PMID 30526847, 2018). "We also showed that overexpression of SETD3 promoted tumor cell migration, whereas inhibition of PLK1 activity compromised these phenotypes." (PMID 35912180, 2022). "It should be noted that data extracted from the TCGA database revealed that USP27 or SETD3 expression was notably higher in a variety of tumor types compared to matched TCGA normal tissues and GTEx data." (PMID 35018513, 2022). "We further showed that overexpression of SETD3 promoted tumor cell proliferation and migration, whereas inhibition of PLK1 activity attenuated these phenotypes caused by SETD3." (PMID 35912180, 2022). "The Matrigel transwell invasion assays consistently showed similar results regarding the role of USP27 and SETD3 in the tumor invasion of Hep3B and MHCC97H cells." (PMID 35018513, 2022). "Here, we reported that ubiquitin-specific peptidase 27 (USP27) promotes tumor cell growth by specifically interacting with SETD3, negatively regulating its ubiquitination, and enhancing its stability." (PMID 35018513, 2022). "A number of histone methyltransferases, including Setd3, Setd5, Suv39h2, Smyd3, Prmt3, Prmt6, Nsd1, and Nsd2, were up-regulated in metastases compared to disseminated tumor cells or primary tumors." (PMID 23520493, 2013). "Depletion of FBXW7β or GSK3β increased SETD3 protein levels, thereby facilitating tumor growth." (PMID 35018513, 2022). "In contrast, knockdown of SETD3 reduced cell migration in tumor liver BEL7402 cells." (PMID 35912180, 2022). "Therefore, 18 pairs of human tumor and adjacent liver tissues were collected, and SETD3 and PLK1 levels were examined by Western blot analysis." (PMID 35912180, 2022). "In HCC tissues, circ-SETD3 is another tumor suppressive circRNA that acts as a sponge of miRNA." (PMID 32937886, 2020). "We suggest that within a tumor the regulation of FOXM1 may not only be carried out by SETD3 but also through other molecules." (PMID 32042016, 2020). "However, the mRNA levels of SETD3 in tumours are lower than those in normal tissues based on The Cancer Genome Atlas (TCGA)." (PMID 30795787, 2019). "In addition, overexpression of circ-SETD3 reduced tumor growth in a Huh7 xenograft mouse model." (PMID 32937886, 2020). "We observed that 15 out of 18 pair tissues displayed simultaneously increased SETD3 and PLK1 levels in tumor samples compared to their corresponding adjacent samples." (PMID 35912180, 2022). "In addition to the 8 representative PKMTs with tumor suppressor activity, PRDM16, MLL2, MLL4, SET domain bifurcated histone lysine methyltransferase 1 (SETDB1), SETD3, NSD1, NSD3, DOT1L, SUV39H1, and SUV39H2 have also been suggested to possess tumor suppressor activity." (PMID 38036730, 2023).
infection (2 papers, 2021 to 2022). The state of being infected such as from the introduction of a foreign agent such as serum, vaccine, antigenic substance or organism. "Next, we tested whether the cleavage of eIF4GI by enteroviral 2Apro, which occurs early during infection, is dependent on SETD3." (PMID 35891342, 2022). "SETD3, also a methyltransferase, is a human host protein critical for infection of a wide range of viruses and participates in viral replication yet its mode of action is currently unknown." (PMID 33973408, 2021).
SETD3 also shares sentences with these, for which no sentence is quoted: depression (1 paper); nasopharyngeal carcinoma (1); osteoarthritis (1); renal carcinoma (1); renal cell carcinoma (1); rhabdomyosarcoma (1); Stroke (1); urothelial carcinoma (1).